CGA (glycoprotein hormones, alpha polypeptide)
Diseases named in the same sentence as CGA in open-access papers (continued):
Sharing a sentence is not in itself a finding about the gene and the disease.
tumor (continued). "Elevated serum CgA was reported to be an independent prognostic factor for OS and progression-free survival in CRPC patients treated with abiraterone acetate and was related to advanced tumor stage and higher GS." (PMID 37240468, 2023). "With a sensitivity and specificity ranging between 60 and 90%, CgA represents a crucial blood parameter in NENs of different origins, irrespective of the endocrine activity of the tumor." (PMID 37686593, 2023). "In conclusion, in this large cohort of PNETs we demonstrated that high TNM-stage, tumor grade, Ki67 index, size, CgA, and symptomatic discovery are negative prognostic predictors of survival." (PMID 35837305, 2022). "Markers with >5-fold difference in G3 tumour relative to non-tumour tissue included CD56 (7.2-fold increase), CK6 (7.7-fold increase), CK7 (20.3-fold increase), CK13 (8.5-fold increase), NSE (9.8-fold increase), CgA (5.9-fold increase), laminin (6-fold increase) and Ki-67 (14-fold increase)." (PMID 36362433, 2022). "The CgA staining co-localised with the tumour epithelium, not with the stroma, and was matched with the clinical histopathology reference staining for each patient." (PMID 35909511, 2022). "The previous tumor was a different tumor, which was negative for Syn, CgA, CD56, and Ki-67 on immunohistochemistry, in contrast to NEC components of this tumor." (PMID 34767241, 2022). "In G2, CD56, CgA, NSE, vimentin and Ki-67 were higher in tumour tissue compared to those in non-tumour, and levels of CD44, CD45, CK7, DAXX, synaptophysin and PDX1 were lower in tumour tissue relative to those in non-tumour tissue." (PMID 36362433, 2022). "Studies in murine models of lung carcinoma, mammary adenocarcinoma, melanoma and fibrosarcoma have shown that circulating CgA can be partially cleaved in tumors after the R373 residue, and that the consequent exposure of the PGPQLR373 site is crucial for tumor progression." (PMID 36559048, 2022). "According to histological assessments, there were no statistical differences in tumor grade, mitotic rate, lymphovascular invasion, and immunohistochemical staining for chromogranin A (CgA) and synaptophysin (Syn) between the two groups (all P > 0.05)." (PMID 36632622, 2022). "CgA and NSE have been historically considered circulating tumor markers of NET." (PMID 33903926, 2021). "Based on the patient and tumor features (high percentage of SSTR expression, high proportion of patients with CgA elevation, favorable OS) reported in that study, it can be assumed that a large proportion of the studied population reflect rather NET G3 instead of NEC." (PMID 33923759, 2021). "Case 5 of the metastatic bone lesion from a sporadic case showed fibrous non-osseous stroma embedded by trabecular tumor cells, which were weakly positive for CT, CgA, and SPY (Figure." (PMID 33485291, 2021). "One small sporadic tumor (0.5 cm × 0.3 cm) was strongly and weakly, patchy stained for CgA and SPY, respectively, while larger sporadic tumors were diffusely and strongly stained for CgA and SPY." (PMID 33485291, 2021). "In addition to CgA, pro-GRP is a complementary tumor marker for prognostic and therapeutic monitoring of patients with NE tumors (NETs)." (PMID 33921329, 2021). "The dysplastic-calcified lesion in the middle of the tumor was nonspecifically stained for CT, CgA, and SPY (Figure." (PMID 33485291, 2021).
tumor (continued). "Traditionally, several plasma, serum, and urine markers have been evaluated as predictors of tumor progression in NETs, including 5-hydroxy indole acetic acid (5-HIAA), chromogranin A (CgA), serotonin, neuron-specific enolase (NSE), neurokinin A, E-cadherin, or neuropeptide K." (PMID 32563832, 2020). "CgA-expression was not a significant prognostic marker, despite a statistically significant result in a sub-analysis comparing tumours with heterogeneously positive vs. negative CgA-staining." (PMID 31924180, 2020). "One of the major challenges in the management of NENs is that neither anatomical imaging modalities nor conventional blood biomarkers such as CgA can accurately prognosticate tumour behaviour." (PMID 32291735, 2020). "For CgA, the majority of negatively stained tumours were also negative for SSTR-2a, 28% (n = 45/163)." (PMID 31924180, 2020). "Correlation between chromogranins and inflammatory parameters (high sensitivity C reactive protein, interleukin-6, and white blood cell count) showed that CgA was not correlated with these parameters in any of the tumor groups (p ≥ 0.0824)." (PMID 33383764, 2020). "Compared to neuroendocrine-cell-negative tumors, CgA+ neoplasms have been reported to have worse clinical and pathological properties; and we learn more and more about the role of CgA in non-endocrine tumors every day." (PMID 33383764, 2020). "IHC analysis, such as Syn, CgA, CD56, PYY, and thyroglobulin, could also promote the diagnosis of POC, while in our cases, both tumor tissues were positive for Syn, CgA, and CD56." (PMID 33019380, 2020). "Ki-67 index variation is closely related to the poor prognosis of patients with tumor metastasis, but neither Syn variation nor CgA variation is related to patient prognosis." (PMID 32917216, 2020). "Postoperative immunohistochemistry results showed that the tumor was positive for CgA, CD56, NSE, and SYN, and negative for CK (AE1/AE3), MelanA, ki-67, and s-100." (PMID 32384867, 2020). "Immunohistochemistry revealed that the majority of tumor cells were positive for chromogranin A (CgA) and Synaptophysin (Syn), but negative for cytokeratin markers (CKs), including CK7 and CK20." (PMID 31038858, 2019). "Conversely, the other part of the tumor was strongly positive for CK, but negative for CgA, SYN and CD56, as well as S100." (PMID 31109373, 2019). "In the present study negative correlations were observed between tumor grading and SST2A and CgA expression, and a positive association with CXCR4 and Ki-67 expression." (PMID 30867449, 2019). "As with SST2A, significantly better outcomes were also seen in patients with CgA-positive neoplasms compared to CgA-negative tumors (PT plus MTS, PT and MTS separately: log-rank test: p < 0.001; all other cases log-rank test: p < 0.020)." (PMID 30867449, 2019). "Ki-67 at baseline was not identified as a potentially important prognostic factor for PFS, prior therapy (yes) was not prognostic in the presence of other terms and, notably, CgA at baseline, and tumor grade were excluded from the final model." (PMID 30642293, 2019). "No interrelationship was seen between CgA serum values and CgA expression in the tumor samples (r = 0.039, p = 0.744)." (PMID 30867449, 2019). "There was no statistical difference between false negative and positive CgA for tumor stage, location of tumor or gender, however, age was significantly higher in the positive CgA subgroup (p < 0.001)." (PMID 30564197, 2018). "Interestingly, in ECL cell hyperplasia and NETs there was co-expression of CCKBR and CgA or HDC in almost all normal ECL- cells and ECL-derived tumor cells." (PMID 28980157, 2018). "Interestingly, in case 7, all the stages from ECL cell hyperplasia, NET and NEC were observed, and further examination with IHC and ISH clearly demonstrated positivity for both CgA and CCKBR in all the various components of the tumor." (PMID 28980157, 2018).
tumor (continued). "Guiping Qin demonstrated that the tumor cells are positive for vimentin, CK, CgA, syn, CEA, calcitonin, HMB-45, and S-100 and negative for TG and TTF-1." (PMID 30424779, 2018). "IHC staining in both tumors demonstrated strong positivity for at least one of the neuroendocrine markers (CgA, SYN, CD56, NSE) in more than 80% of tumor cells and at least one of the squamous differentiation markers (P40, P63, CK5/6) in more than 95% of tumor cells." (PMID 29050228, 2017). "Rare events with significantly increased plasma levels of CgA were found at both tumor localizations (colon: n = 5; rectum: n = 10) and did not depend on tumor grading (G1: 8, G2: 3, and G3: 4)." (PMID 29232390, 2017). "Since CgA plasma levels are not sufficient to predict tumor growth or survival in patients with colorectal NEN, we looked for other parameters to stratify these patients." (PMID 29232390, 2017). "The small amounts of CgA expressed in L cells are probably sufficient to reveal a positive signal in immunohistochemistry but not enough to lead to a significant rise of CgA plasma levels documenting a significant tumor growth." (PMID 29232390, 2017). "Even after confirmed tumor progression with increasing tumor load in the liver, in most patients plasma levels of CgA were not or only slightly elevated but do not exceed the threshold of 50 U/l." (PMID 29232390, 2017). "72h treatment of cells with 1nM octreotide or 1nM pasireotide alone similarly decreased CgA secretion as previously observed, except in one primary culture which do not respond to SSAs (tumor 2)." (PMID 28454119, 2017). "Taken together, CgA is a valuable marker for immunohistochemical diagnosis, but CgA plasma concentration is not suitable to mirror tumor burden or prognosis in patients with NEN of the colon and rectum." (PMID 29232390, 2017). "In the past, several plasma, serum and urine markers have been evaluated as predictors of tumor progression in NEN, such as chromogranin A (CgA), serotonin, 5-hydroxyindoleacetic acid (5-HIAA), neurokinin A, neuropeptide K, neuron-specific enolase, or E-cadherin." (PMID 29232390, 2017). "As reported in our study and in contrast to tumor located in the small bowel and pancreas, plasma levels of CgA in colorectal NEN are not significantly elevated." (PMID 29232390, 2017). "In less differentiated neoplasms (G3) of the colon and rectum the staining for either synaptophysin or CgA was mostly focal or negative (50% and 55.6%) but less intense compared to the well-differentiated tumors." (PMID 29232390, 2017). "We show that full-length CgA, but not fragments lacking the C-terminal region, can inhibit tumor growth in all these models, with U-shaped dose-response curves, and we provide evidence that an active site is located in the C-terminal region." (PMID 27683038, 2016). "The tumor cells immunestained was positive for HMB-45, focally positive for c-Kit (CD117), and negative for vimentin, S-100, AE1/AE3, CK-7, CK-18, CD-10, RCC antigen, CgA, DOG-1, EMA, smooth muscle actin, and synaptophysin." (PMID 27858882, 2016). "Since PACC can have heterogeneous tumor populations, which include neuroendocrine derived cancer cells, we stained for neuroendocrine markers, such as neuron specific enolase (NSE) and chromogranin A (CgA)." (PMID 27165126, 2016). "Collected data revealed that CgA expression in tumor tissue was available in 78 patients with 35 negative and 43 positive expression (a sensitivity of 55.1%)." (PMID 27159453, 2016). "The expression of HNF1A-AS1 in tumor samples was also significantly correlated with one immunohistochemical markers of cancer, RRM1 (p = 0.006), but not with VEGF, C-erbB-2, TS, BRCA1, ERCC1, Ki67, CD56, Syn, or CgA." (PMID 26472090, 2015). "Patients with FIGO stage I–IIA tumors, tumor size ≤4 cm, negative CgA status, no lymph node metastasis and infiltrating depth of <1/3, exhibited a better prognosis." (PMID 25435939, 2015).
tumor (continued). "In our study, expression of CgA and Syn in polygonal tumor cells was observed in only one case, and no electron dense granules of typical neuroendocrine particle morphology were observed under the electronmicroscope." (PMID 25130377, 2014). "Additional immunohistochemical staining demonstrated that the tumor was positive for synaptophysin, chromogranin (CgA), cytokeratin and CD56, and negative for S-100." (PMID 25523133, 2014). "Further immunohistochemical analyses showed that tumor cells stained positive for Syn and CD56, which are neuroendocrine markers, while no staining for CgA indicated that the tumor was poorly differentiated." (PMID 24884973, 2014). "The immunohistochemical staining in these tumor cells was positive for CgA and Syn and negative for CEA, HPC and AFP." (PMID 24944650, 2014). "CgA is constitutive component of neuroendocrine secretion, not proliferation, and therefore its use as a surrogate marker for tumor growth has obvious limitations." (PMID 23691035, 2013). "Although CgA is a well-characterized product of NENs, very few studies have investigated the role of either CgA or its cleavage fragments as regulators of small intestinal NEN (SI-NEN) proliferation, the commonest tumor in this class." (PMID 24260544, 2013). "While CgA is commonly considered a marker of tumor load and plasma levels are related to progression free survival in GEP-NENs, this most likely reflects tumor mass per se." (PMID 24260544, 2013). "CgA PCR analysis detected the presence of CgA transcripts in lymph nodes without histological evidence of tumor metastasis." (PMID 22720672, 2012). "5-HIAA and CgA showed comparable sensitivity in midgut NETs, while AP does not seem to be useful as a tumor marker in GEP-NETs." (PMID 24213232, 2012). "In the future, all patients should discontinue PPI use in order to obtain a reliable CgA level, irrespective of tumour activity or duration of PPI use." (PMID 21989216, 2011). "An increasingly evaluated prognostic marker for NET, the tumour marker CgA, was not included in our analysis as it was not available for many patients." (PMID 17406366, 2007). "All tumours were negative for neuroendocrine markers such as Syn, CgA, and NF." (PMID 38291475, 2024). "Immunohistochemical staining showed tumor cells positive for chromogranin A (CgA) and synaptophysin; no malignant features, such as lymphovascular invasion, significant atypia, or mitotic activity, were noted, leading to a diagnosis of a typical bronchial carcinoid tumor." (PMID 39233931, 2024). "However, chromoprotein granules (CgA), neuron-specific enolase (NSE) and 24h-5 hydroxy-indole acetic acid (5-HIAA) are effective methods for the diagnosis of NENs, which are related to tumor size and stage, and NSE and CgA can even predict postoperative recurrence." (PMID 38807765, 2024). "Moreover, the application of CgA is not sufficient to predict tumor relapse for medullary thyroid NETs and lung NENs." (PMID 37685358, 2023). "In addition to those findings, a strict and consequent follow-up, including laboratory testing of CgA before primary surgery and during each follow-up appointment and repeated imaging with at least a PET-CT scan once a year, helps to detect tumor recurrence early." (PMID 37077861, 2023). "As expected, the CgA staining could be detected within the cytoplasm and not the nucleus of the tumour cells (magnified panel)." (PMID 35909511, 2022). "Factors which might cause this difference in our small study cohort in comparison to the RADIANT-3 trial data might be tumor grading, percentage of patients with high baseline NSE 1 × ULN or high baseline CgA 2 × ULN, as well as late treatment line with everolimus." (PMID 36289880, 2022). "Furthermore, SST4 expression in the tumours negatively correlated with serum serotonin values (rsp = − 0.322; p = 0.023), but not with serum chromogranin A (CgA) values (rsp = − 0.106; p = 0.380)." (PMID 36042228, 2022).
tumor (continued). "This relatively limited tumor spread may be a reason for not presenting highly elevated serum CgA levels in MTC patients." (PMID 33485291, 2021). "CgA staining was absent in non-tumour tissue but many cells in the tumour tissue were stained." (PMID 33906633, 2021). "Tumor progression during follow-up was not accompanied by increasing CgA levels." (PMID 34690926, 2021). "However, we used cross-sectional analysis for the change of CgA to predict tumor progression that was not interfered with by the fluctuation of CgA level during serial follow-up." (PMID 34868938, 2021). "However, most tumor cells produce non-specific substances, such as chromogranin A (CgA) and neuro-specific enolase (NSE)." (PMID 34868938, 2021). "Indeed, CgA was not predictive of change in tumor burden in our cohort, confirming the need for better predictors." (PMID 33809226, 2021). "The study did not validate CgA as a surrogate marker of tumor progression." (PMID 34868938, 2021). "Interestingly, in our analysis miR-29b levels were further decreased in patients with higher CgA levels but did not reflect the tumor localization, the tumor proliferation activity nor any other clinicopathological tumor features." (PMID 32899973, 2020). "In patients with cancer of unknown primary, a large proportion of tumours were strongly positive for CgA (67%), and negative for SSTR-2a (70%)." (PMID 31924180, 2020). "CgA and the N‐terminal fragment of vasostatin‐1 can enhance the endothelial barrier function, exert antiangiogenic effects, and inhibit tumor growth in animal models, whereas CgA fragments lacking the CgA C‐terminal region promote angiogenesis and tumor growth." (PMID 31588572, 2019). "Due to the significant effect of focal NED on disease-specific and overall survival outcomes in some of the included studies in our review, serum neuroendocrine markers such as CgA and NSE might be considered as tumor markers for monitoring of PC patients who harbor focal NED on their RP." (PMID 30893781, 2019). "However, measurement of these biologically active amines is not suggested for screening; generic tumor markers, such as CgA, can be increased in several clinical conditions, possibly leading to false positives." (PMID 31382663, 2019). "However, plasma CgA is a poor marker to follow-up these patients because only a minority exhibited increased levels which did not increase significantly during tumor progression." (PMID 29232390, 2017). "Anti-human CgA410-439 immunoglobulins (Igs), but not control Igs, could block the anti-tumor activity of exogenous CgA in the WEHI-164 model." (PMID 27683038, 2016). "The lack of effects on tumor cell proliferation and viability in vitro argues against the hypothesis that neoplastic cells are primary targets of CgA in our models." (PMID 27683038, 2016). "The results may be an indicator that CgA measurement alone may not adequately reflect tumor response to therapy." (PMID 27159453, 2016). "When no immunoreactive tumor cells for CgA and Syn were noted, the tumor was designated as NED(−)." (PMID 25093184, 2014). "Blood samples demonstrated a lower chromogranin A (CgA) serum expression in mice which had been injected with NAP1L1-knockdown cells (p < 0.05) suggesting that CgA may, as in humans, be a marker of tumor burden." (PMID 25071868, 2014). "Another study also implied that not all CgA(+) tumor cells were also Syn(+)." (PMID 25093184, 2014). "However, consensus guidelines also note that such G3 tumours often have very high Ki67 immunoreactivity and that the patients rarely have hormonal syndromes and usually have negative serum markers (such as CgA) and negative somatostatin-receptor scintigraphy." (PMID 24683485, 2014).